IL13 (interleukin 13)
Diseases named in the same sentence as IL13 in open-access papers (continued):
Sharing a sentence is not in itself a finding about the gene and the disease.
infection (continued). "Individuals who were untreated and those who received a single dose of PZQ had higher IL-5 levels and a trend towards higher IL-13 levels in response to schistosome antigen AWA compared to people without infection at the two-year follow up who had not been treated." (PMID 39250522, 2024). "Pro-inflammatory (IFNγ, IL-6, TNFα), Treg (IL-10, TGFβ1, TGFβ3), Th9 (IL-9), Th17 (IL-17), and Th2 (IL-4, IL-13) cytokines, total IgM and IgG, as well as gene expressions of FoxP3, STAT5+, IFNγ-R1, and ROR alpha+, were measured at day 1, day 7, day 14, day 21, and day 28 post-infection." (PMID 37569646, 2023). "Notably, infection of neonatal mice with RSV enhanced the airway hyperreactivity response to subsequent allergen challenge, with higher eosinophil, macrophage and CD4+ T cell accumulation and elevated IL-4, IL-5 and IL-13 cytokines." (PMID 37795093, 2023). "As the Salmonella cell wall contains trehalose phospholipids that bind to and activate MINCLE, it is possible that induction of IL-17-producing cells during infection requires MINCLE and may be inhibited by schistosome eggs through IL-4/IL-13-induced downregulation of the receptor." (PMID 36753434, 2023). "Also in line with our results from pre-patent infection, a significant reduction in expression of Th2 cytokines IL-4, IL-5 and IL-13 was observed in cDC2 depleted Cre+ mice as a proportion of CD4+ T cells, and as absolute number for IL-5 and IL-13." (PMID 37012228, 2023). "In addition, the levels of type II cytokines such as IL-4, IL-13, and IL-10 in infected wild-type mice were significantly higher than in the control mice without infection (P < 0.05)." (PMID 36271450, 2022). "Others, such as IL-1α, IL-2, IL-7, IL-9, IL-10, IL-12p40, IL-13, and VEGF were present at equivalent concentrations in lungs of infected and control mice during the first 5 days, but at significantly reduced concentrations in lungs of infected mice at day 7 post-infection." (PMID 35812400, 2022). "Groups of C57BL/6 mice treated throughout infection with neutralizing antibodies for either IL-4 or IL-13, but not mice treated with an IgG control, showed elevated ALT levels at day 7pi suggesting a direct role of these cytokines in limiting liver injury during early acute infection." (PMID 36159876, 2022). "IL-13 did not have a major effect on collagen dynamics during the early phase of infection." (PMID 34127548, 2021). "Here we analyzed ILCs excluding NK1.1+ subset, and we found no significant changes or induction of IFN-γ or IL-13 production from ILCs after infection, suggesting that these cytokine secreting ILCs probably are not major players in the early immune response to L. major in C57BL/6 mice." (PMID 34699567, 2021). "Furthermore, a lack of vitamin A led to a significant increase in IL-13-producing ILC2s and T. muris resistance; therefore, nutritional stress can be beneficial in response to parasite infections through ILC2 development." (PMID 34451389, 2021). "However, this impairment was not sustained during the course of infection as it disappeared at subsequent infection time points (U = 6, P = 0.6857; U = 1, P = 0.4 for IL-5 and U = 3, P = 0.2; U = 1, P = 0.4 for IL-13 at 9 and 12 wpi, respectively)." (PMID 33482904, 2021). "Furthermore, our transcriptional profiling predicted a dysregulation of the transcription factor Foxa2 in the absence of IL-13 after infection." (PMID 34127548, 2021). "Consistent with previous findings, epithelial cells were the major source of RELM-α at these time points, whereas other cellular sources such as alveolar macrophages, neutrophils, and eosinophils, were relatively unchanged in the absence of IL-13 after infection (data not shown)." (PMID 34127548, 2021). "Moreover, infection of B.1.1.7 and B.1.351 resulted in significant elevation of several key inflammatory cytokines in K18-hACE2 mice, including TNF-α (lung), IL-1β (lung), IL-6 (lung and liver), IL-13 (liver), IFN-α (liver) and IFN-β (liver)." (PMID 34772941, 2021).
infection (continued). "Knockout of IL-13 gene, but not adoptive transfer of CD4γ13 or CD8γ13 T cells, may affect important immune cells in anti-infection immunity." (PMID 34093528, 2021). "To directly test whether IL-13 was deleterious following SARS-CoV-2 infection, we administered i.p. injections of anti–IL-13 or isotype-matched control IgG on days 0, 2, and 4 after infection." (PMID 34185704, 2021). "A direct requirement for IL-4/IL-13 signaling in worm expulsion is demonstrated by IL-4 receptor antibody blocking experiments, and in IL-4R−/− and STAT6−/− mice, dramatically limiting worm expulsion during T. muris, Heligmosomoides polygyrus or N. brasiliensis infection." (PMID 33193437, 2020). "Further IL-4/IL-13 stimulation does not upregulate SIGNR3 expression or enhance infection." (PMID 31825972, 2019). "Examination of RNA expression of known surface receptors that bind and internalize filoviruses demonstrated that IL-4/IL-13 stimulated expression of the C-type lectin receptor DC-SIGN in human macrophages and addition of the competitive inhibitor mannan abrogated IL-4/IL-13 enhanced infection." (PMID 31825972, 2019). "Our previous study described that co-infected Ss infection with active or latent TB has significantly reduced Type 1 (IFN-γ, TNF-α, and IL-2), Type 17 (IL-17A and IL-17F) and increased regulatory as well as Type 2 (IL-4, IL-5, and IL-13) cytokines when compared to TB infection alone." (PMID 30897083, 2019). "Inconsistent with this hypothesis, at day 6 post-infection, we did not observe any significant changes to IL-5 and IL-13 mRNA or protein producing CD4 T cells or ILCs in the lungs of infected RELMα-deficient mice during this peak reparative phase." (PMID 30500858, 2018). "Neither acute nor chronic IL-13 treatment changed IP-10 in the presence of infection." (PMID 29721720, 2018). "Mice of a C57BL/6 background (B6.WT) display a localized, self-healing infection characterized by interferon-γ (IFN-γ) production, while mice of the BALB/c background respond to infection with a preferential production of Th2 cytokines, such as IL-4, IL-10, and IL-13." (PMID 29403488, 2018). "As previously reported, in the clinical infection, the bovine MAP infection disease was characterized by a gradual shift in the immune responses from cell-mediated immune response to antibody mediated immune response while IL4, IL5 and IL13 can promote the Th2 antibody-mediated immune response." (PMID 30591025, 2018). "Consistent with the lack of an eosinophilic response, IL-5 and IL-13 levels were not significantly elevated in the PVM-infected RAGE deficient mice (p=0.7016 and p=0.9973) Levels of IL-17A were also not elevated in RAGE deficient mice upon infection with PVM." (PMID 28099113, 2017). "In addition, IL-13-producing ILC2s were shown to cooperate with CD4+ T cells during N. brasiliensis infection to mediate larval killing in the small intestine during primary infection and in the lung following secondary infection." (PMID 29163497, 2017). "Similarly, IL-5, IL-13, periostin (a marker of type-2 inflammation) and eotaxin-2 were not increased in RAGE deficient mice upon re-infection with PVM (p=0.8815, p>0.9999 and p>0.9999)." (PMID 28099113, 2017). "T-bet/IFN-γ co-expressing cells were detected in similar proportions within IL-4 and IL-13 producers from spleens of mice infected for 10 days and the frequencies of IFN-γ+ Th2/1 hybrids in Th2 cytokine producing populations were similar when comparing day 10 and 20 post infection." (PMID 28676845, 2017). "CD4+ T cells but not ILC2 expressed detectable amounts of IL-13 at this stage of infection." (PMID 29045902, 2017). "Whilst T helper cells could obviously not be measured in antibody treated mice, an absence of induction of Il4, Il13 and Il17a mRNAs in the lung following infection supported an absence of Th2 and Th17 responses in CD4+ cell depleted mice." (PMID 27683080, 2016).
infection (continued). "Levels of IL-2, IL-4, IL-5 and IL-13 were unaltered by infection in the presence or absence of Mtb." (PMID 26894562, 2016). "While this might have been the case in STAT-6−/− animals in which numbers of IFN-γ+ CD4 cells substantially increased following infection with the mutant virus, it did not hold true for the IL-13−/− mice." (PMID 25751266, 2015). "With the progression of the infection a more equilibrated immunological balance is observed, with 6 genes showing significant transcription up-regulation: IFN-γ, IL-5, TNF-α, TGF-βR1, IL-21 and IL-23 and 4 extra genes showing significant down-regulation: DEFB1, CD163, IL-13 and IL-18." (PMID 26589145, 2015). "However, infection induced the type 2 cytokine IL-13 and the AMP Retnlb and Ang4 (not shown) in both Jackson and NCI mice." (PMID 26377648, 2015). "Furthermore, peptidase-specific cytokine secretion, particularly the Th2 cytokines IL-4, IL-5, IL-13, was also observed in the immunized mice at 6 days after infection but not in the non-immunized mice." (PMID 24465551, 2014). "Expression levels of interleukin (IL)-4, IL-10, IL-13 and tumor necrosis factor (TNF)-α were significantly up-regulated while interferon (IFN)-α, IFN-β, IFN-γ, IL-1β,IL-2, IL-3, IL-15, IL-17F, IL-18 and colony-stimulating factor (CSF)-1 were markedly decreased in PBMCs at all stages of infection." (PMID 24358317, 2013). "Protection against secondary infection depended on IL-4Rα and IL-13; but not IL-4." (PMID 24204255, 2013). "Indeed, in contrast to Itgb8 (CD11c-Cre) mice, no enhancement of CD4+ T-cell IL-13 production was observed early during infection in Foxp3+ Treg-depleted mice." (PMID 24098124, 2013). "Importantly, at the infection site, in the absence of Tfh cells, we found that ICOS deficiency actually led to an increased percentage of CD4+ T cells producing IL-4 and IL-13 protein." (PMID 23319295, 2013). "However, basophils may play a major role in type-2-mediated secondary infection in conjunction with CD4+ T cells, as depletion of IL-4 and IL-13 in both basophils and CD4+ T cells was necessary to abrogate protection." (PMID 22360486, 2012). "CD4+ T cell specific (LckcreIL-4Rα−/lox) IL-4Rα−/− mice are more resistant than global IL-4Rα−/− mice to infection with L. major, indicating that in the absence of a polarized Th2 response, there is a role for an IL-4/IL-13 responsive non-CD4+ T cell in early resistance to infection." (PMID 21245915, 2011). "In response to infection (LCL-Vacc), all cytokines, with exception of IFN-γ, were detected in all clones and, similarly to the response to low antigen concentration (peptide at 5 ng/ml), GM-CSF, TNF-α, IL-13 and IL4 were detected at 48 hours at significantly higher levels than those at 6 hours." (PMID 21931646, 2011). "The absence of IL-13 had profound effects during the early stages of infection." (PMID 21573182, 2011). "Notably, the expression of IFN-γ and IL-10 were not different between naïve WT and IL-13−/− mice and the onset of IFN-γ and IL-10 production was not affected by the absence of IL-13 during the early stages of infection." (PMID 21573182, 2011). "To conclude in this study utilising tissue specific IL-4Rα−/− mice we demonstrate that upon infection with L. mexicana initial lesion growth is dependent on a non-CD4+ T cell population responsive to IL-4/IL-13, while progressive infection is dependent on CD4+ T cells responsive to IL-4." (PMID 21245915, 2011). "However, we could not detect any IL-4 or IL-13 cytokine release from mLN Treg cells after secondary infection while Treg cells of both genotypes released equivalent amounts of IL-10 suggesting fully functional Treg cells in RelBΔDC mice." (PMID 39443450, 2024).
infection (continued). "Although gross changes in lung structure were not evident at day 6 between WT and Il13−/− mice, it is feasible that changes to physical lung injury in the absence of IL-13, as was seen on D2 post-infection, could have profound effects on the way in which the lung repairs compared with WT animals." (PMID 34127548, 2021). "Similarly, VEGF correlated positively with IFN-γ, IL-13 and IL-16 in BS0–II in the absence of systemic infection or substantial tangle pathology but the association was again lost in BSIII–IV and V–VI, and even sooner, in BS0–II, in cases with infection." (PMID 33723589, 2021). "Furthermore, only STAT1+/+ mice developed M2 macrophages at 8 weeks post-infection, although macrophages from both T. crassiceps-infected STAT1+/+ and STAT1−/− mice responded to IL-4 in vitro, and both groups of mice were able to produce the Th2 cytokine IL-13." (PMID 34684235, 2021). "This is in contrast to worm (Trichinella spiralis) infection, during which IL-13, but not IL-4, is affecting murine goblet cell proliferation, pointing to that the combined effect of the pathogens and the immune system determines the mucin/mucus changes during infection." (PMID 30665337, 2019). "However, there was a significant decrease in the total lung concentration of IL-13 in the RSV-infected IL-33 KO mice compared with RSV-infected WT mice (Fig E5, D), highlighting an equivocal role for IL-33 during RSV-induced ILC2 activation in our murine model of infection." (PMID 27156176, 2016). "Interestingly, neutralization of TSLP significantly attenuated IL-13+ ILC2 induction during RSV infection irrespective of whether intervention occurred 6 or 36 hours after infection." (PMID 27156176, 2016). "Consistent with the leukocyte responses, we observed no significant increases in IL-4 or IL-13 gene expression in the livers or intestines (not shown) of IL-4Rαflox/ΔLysMCre mice when compared with expression in IL-4Rαflox/Δ littermate controls 9 and 16 weeks post-infection." (PMID 25211233, 2014). "An up-regulation of the transcription of the IL-13 receptor (Il13ra1) was observed by 15 min post Δ-mce1 H37Rv-infection however, a corresponding change in the concentration of IL-13 measured in the supernatant could not be detected during the first hour post Δ-mce1 H37Rv-infection." (PMID 22039457, 2011). "For the cytokines Rantes, GM-CSF, Eotaxin, IL-13, IL-9, IL-6 and IL-1b there was no significant mean difference in concentration among the first three time-points (15 min, 30 min and 60 min) and the last two time-points (4 hrs and 10 hrs) for both the H37Rv and Δ-mce1 H37Rv-infections." (PMID 22039457, 2011). "As expected, a classical Th2 cytokine profile with up-regulation of IL-5, IL-13 and to a lesser extent of IL-4, but with no changes in IFNγ transcript levels, was observed in these pooled samples with expression levels peaking after the third immunising infection and immediately after challenge." (PMID 20950493, 2010). "CCL-2 exhibited heightened levels on day 1 post-infection, while IL-1β, IL-13 and CCL11 showed increased levels on both day 1 and 4 post-infection, as compared to the non-infected group." (PMID 39038037, 2024). "Restimulation of mesenteric lymph node (mLN) cells 21 days post-infection (p.i.)with anti-CD3/CD28 induces the production of type-2 cytokines, such as IL-4, IL-5, and IL-13, in cells derived from WT mice but not in A20myel-KO mLN cells." (PMID 38680500, 2024). "In contrast, IL-1RA, IL-7, IL-13, and G-CSF were decreased in the merged SIDS cases compared to control cases without evidence of infection." (PMID 35986144, 2023). "In the MLN, infection induced a clear Th2 response, shown by increased expression of the Th2 master transcription factor GATA3 and the Th2 cytokines IL-5 and IL-13 in CD4+ CD44hi cells, and this response was not affected by the blockade of IL-10 signalling." (PMID 35428872, 2022).
infection (continued). "In line with a reduced ability to produce alternatively activated macrophages, infection-induced levels of RELMα were reduced in the BAL of Ptpn2-LysMCre mice, while IL-4 and IL-13 were not affected and IL-6 and IL-17 were elevated." (PMID 34420044, 2022). "Three cytokines, namely interleukin-5 (IL-5), interleukin-13 (IL-13) and macrophage inflammatory protein-2 (MIP-2), were not significantly affected by the infection." (PMID 33919457, 2021). "In controls, IL-5, GM-CSF, IL-13 and IFN-γ were elevated in brains from control subjects with compared to those without infection." (PMID 33723589, 2021). "PDGFRβ correlated negatively in BSIII–IV and positively in BSV–VI with several cytokines (IL-10, IL-12, IL-13, IL-2, IL-4 and TNF-α) but only in the absence of infection." (PMID 33723589, 2021). "The peak of IL-13, IFNγ, and TNF levels in the BALF was at day 11 or earlier in adult mice infected with P. murina but not until day 28 post-infection in mice infected as pups (Figure A3A–C)." (PMID 34682248, 2021). "In contrast, infection with rVSV/G, expressing native VSV G glycoprotein, was not enhanced by IL-4/IL-13 stimulation, suggesting that the increase in infection is specific to EBOV glycoprotein-expressing virus." (PMID 31825972, 2019). "We further demonstrate both in vivo and in vitro that IL-4/IL-13 enhances EBOV GP specific entry, as rVSV/G infection of mice and pmacs were not altered by these cytokines." (PMID 31825972, 2019). "We found that IL-4/IL-13-stimulated macrophages were more robustly infected by rVSV/EBOV GP as compared to non-polarized controls, with a 3-4-fold increase in infection observed." (PMID 31825972, 2019). "In the absence of infection, addition of IFN-γ and TNF-α trended towards decreasing the amount of incorporated label, IL-13 had no apparent effect, while IL-4 increased the mucin production and transport speed en route exocytosis (p < 0.001)." (PMID 30665337, 2019). "Mannan, but not GalNac, inhibited IL-4/IL-13-dependent enhancement in pmacs, providing evidence that a mannose binding CLR such as SIGNR3 was responsible for the cytokine-dependent increase in infection." (PMID 31825972, 2019). "While ST2−/− mice had normal numbers of ILC2s in their colons, their ILC2s were dysfunctional as evidenced by their lack of IL-13 expression, indicating ST2−/− mice have reduced functional capacity during infection." (PMID 31221971, 2019). "Combined with our previously reported results, it is evident that HHV-8 can undergo limited, nonproductive infection of myeloid-origin DC (i.e., MDDC) and macrophages (i.e., IL-13-activated MDM) while productively infecting LC and iDDC." (PMID 28768873, 2017). "In sharp contrast, the i-Raptor−/− mice did not respond to Tm infection as demonstrated by the lack of DCLK1 expression and IL-25 in epithelium and IL-13 in lamina propria." (PMID 28717211, 2017). "Despite the increased immunity to infection in Setd7-/- mice, we did not detect any significant differences in expression of TH1 cell- or TH2 cell-mediated cytokine genes such as Ifng and Il13 in the gut by qPCR." (PMID 27598373, 2016). "Furthermore, P4-treatment did not activate markers of ILC2s, including IL-13 and IL-33 production, or increase numbers of Tregs in the lungs during infection, suggesting that the induction of AREG in response to P4 may not be occurring in these immune cell populations." (PMID 27631986, 2016). "Infection of both neonatal and infant, but not adult, BALB/c mice increased the expression of IL-13 in the lungs, the numbers of mucus secreting cells (MSC) around the airways and AHR during AAD in later-life." (PMID 22870337, 2012). "In particular, the expression of IL13 and RETNLB was significantly increased in infected pigs, regardless of diet (main effect of infection with a fold change of 3.7 and 1.7, respectively), and the expression of CCL26, IL10 and TFF2 also tended to be increased." (PMID 38081984, 2023).